INS (insulin)
Diseases named in the same sentence as INS in open-access papers (continued):
Sharing a sentence is not in itself a finding about the gene and the disease.
Insulin resistance (continued). "Insulin resistance in obesity is characterized by decreased insulin-triggered glucose transport and processing in skeletal muscles and adipocytes, as well as inefficient hepatic regulation of glucose synthesis." (PMID 40725244, 2025). "In OA, especially under conditions of obesity and insulin resistance, iHSP70 expression is suppressed due to impaired insulin signaling, while eHSP70 is elevated, contributing to synovitis, cartilage degradation, and disease progression." (PMID 41472751, 2025). "The correlation matrix illustrates the core features of MetS, showing strong positive associations between anthropometric indices, insulin resistance (HOMA-IR and insulin), sdLDL-C, and inflammatory markers (CRP and C3)." (PMID 41155195, 2025). "This dynamic process begins with insulin resistance in a prediabetic state, with β-cells compensating by increasing insulin secretion." (PMID 41357171, 2025). "Insulin resistance refers to reduced sensitivity of peripheral tissues to the effects of insulin, leading to compensatory hyperinsulinemia and eventual glucose intolerance." (PMID 40732323, 2025). "In recent years, several negative regulators of insulin action that contribute to insulin resistance in obesity and type 2 diabetes have been identified, including protein tyrosine phosphatase 1B (PTP1B)." (PMID 40137124, 2025). "It is characterized by cell inability to respond to insulin, which is known as insulin resistance, and with time, leads to β-cell altered production of insulin." (PMID 40943066, 2025). "Studies have shown that during insulin resistance, the vasodilatory effects of insulin are reduced, while its activation of the sympathetic nervous system and renin-induced sodium reabsorption remains intact." (PMID 40862144, 2025). "It is characterised by insulin resistance, where the insulin-sensitive tissues fail to respond effectively to insulin, coupled with a progressive decline in pancreatic insulin production." (PMID 41149292, 2025). "Normal-weight patients carrying the homozygous reference allele and the variant of rs2289669 presented a greater decrease in fasting insulin and insulin resistance index (HOMA) as compared to heterozygotes." (PMID 40943569, 2025). "The onset of T2DM begins with insulin resistance, where cells like hepatocytes, adipocytes, and muscle cells fail to respond effectively to insulin." (PMID 40363798, 2025). "Current research underscores the importance of enhancing insulin production in pancreatic beta cells and reducing insulin resistance as fundamental strategies for managing T2DM." (PMID 40540468, 2025). "Of particular importance, this dyslipidemic state seems to be closely connected with insulin resistance, as evidenced by the concurrent elevations in glucose, insulin, and HbA1c levels." (PMID 41468519, 2025). "Our study shows that women with folate excess had higher hPL and PRL (both primarily promote insulin secretion, although hPL has also been reported to promote insulin resistance) compared to women whose folate was within the normal range." (PMID 40944254, 2025). "The remaining 22.5% had the Severe Insulin-Resistant Diabetes (SIRD) subtype, distinguished by elevated BMI, marked insulin resistance, increased insulin secretion, and relatively well-controlled HbA1c levels." (PMID 40678231, 2025). "The observed levels of insulin, insulin resistance and beta-cell function were highest for participants with T2DM without malaria." (PMID 40802820, 2025). "These mice exhibited insulin resistance, characterized by a reduction in insulin-stimulated glucose uptake in skeletal muscle." (PMID 41155203, 2025). "Excessive weight gain in GDM leads to higher fasting glucose and insulin therapy rates, due to increased insulin resistance." (PMID 40225328, 2025).
Insulin resistance (continued). "Like the female T2DM patients, two phenotypes were observed in the male population: obesity-related phenotype with severe insulin resistance; and normal weight phenotype with improved insulin sensitivity." (PMID 39913381, 2025). "Although regulation of HGP plays a more important role in reducing insulin resistance than muscle glucose uptake, enhancing muscle glucose utilization also helps improve insulin sensitivity." (PMID 40299427, 2025). "MIF rs1007888 has been associated with insulin resistance and β-cell dysfunction, while ARAP1 rs1552224 has been linked to reduced insulin secretion." (PMID 41036138, 2025). "Another study reported that daily consumption of probiotic yogurt by pregnant women for 9 weeks stabilized serum insulin levels, suggesting potential prevention of pregnancy-induced insulin resistance." (PMID 40538587, 2025). "Peripheral insulin resistance and compensatory hyperinsulinemia: Chronic sympathetic activation and NE release contribute to hepatic gluconeogenesis and skeletal muscle insulin resistance." (PMID 40869170, 2025). "During pregnancy, insulin resistance leads to increased insulin production to keep glucose levels stable." (PMID 40913218, 2025). "Pathways related to D-Glucose 6-Phosphate also include choline metabolism in Choline metabolism in cancer signaling pathway, insulin secretion, insulin resistance, and thyroid hormone synthesis." (PMID 41199947, 2025). "The pathophysiology of NODAT is characterized by a combination of factors, including impaired insulin secretion, increased insulin resistance, and damage to pancreatic beta cells." (PMID 39941214, 2025). "In terms of metabolic indicators, insulin levels, homeostasis model assessment of insulin resistance (HOMA-IR), and hemoglobin A1c (HbA1c) were all significantly higher in the dyslipidemia group compared to the normal group (p < 0.05)." (PMID 39859220, 2025). "GLP-1 primarily regulates blood glucose levels by promoting insulin production, enhancing insulin sensitivity, and alleviating insulin resistance (49, –, 51)." (PMID 40488467, 2025). "When insulin resistance occurs in the body, the pancreas secretes excessive insulin compensatorily, resulting in hyperinsulinemia." (PMID 41377946, 2025). "Studies have shown that GDM patients have significant insulin resistance, which is manifested by increased fasting blood glucose, fasting insulin, and HOMA-insulin resistance and decreased HOMA-b levels." (PMID 41488068, 2025). "Taken together, these studies demonstrate that insulin resistance during T2Dx impaired GLUT4 trafficking to the cell surface not only in insulin-sensitive tissue but also in the lung." (PMID 41295303, 2025). "For instance, it has been shown that anti-diabetic drugs counteracting insulin resistance (i.e. metformin) seem to decrease PDAC risk, whereas the ones aimed to circulating insulin enhancement (i.e. insulin analogs) manifest an increased risk." (PMID 39828692, 2025). "At the molecular level, insulin resistance is characterized by defects in the insulin signaling pathway, which begins with insulin binding to its receptor on the cell surface." (PMID 39940428, 2025). "Skeletal muscle is a major site for insulin-stimulated glucose uptake, and reduced muscle function and/or mass can lead to a decreased glucose utilization and increased insulin resistance, promoting type II diabetes." (PMID 41300993, 2025). "↓ Insulin levels, ↓ homeostatic model assessment of insulin resistance (HOMA-IR), ↓ homeostasis model assessment of β-cell function, ↓ plasmatic nitric oxide and ↓ GSH levels, improved lipidic metabolism." (PMID 40722870, 2025). "T2D is characterized by increased insulin resistance combined with impaired insulin secretion, leading to excessive glucose accumulation in the bloodstream and subsequent organ damage." (PMID 40430489, 2025).
Insulin resistance (continued). "Caloric restriction and intermittent fasting have been shown to improve cardiovascular outcomes by decreasing insulin resistance and increasing insulin sensitivity, potentially enhancing endothelial function, especially in obese patients." (PMID 41573513, 2025). "Adipose tissue, especially visceral fat, secretes pro-inflammatory cytokines like TNF-alpha and IL-6, which promote systemic insulin resistance by disrupting insulin signaling pathways in muscle, liver, and fat tissue." (PMID 40395625, 2025). "Studies reported elevated triglycerides, fasting glucose, insulin, γ-glutamyltransferase, and insulin resistance indices in MASLD groups." (PMID 41583302, 2025). "T2DM has traditionally been characterized as a metabolic disorder, marked by chronic hyperglycemia, insulin resistance, and a progressively diminishing insulin secretion from the pancreas." (PMID 40951582, 2025). "Insulin resistance not only results in diminished insulin signaling within the central nervous system but also triggers a cascade of alterations in brain metabolism." (PMID 40101022, 2025). "According to these findings, it can be concluded that NADPH oxidase is a very important modulator of the insulin signaling pathway, and represents a significant link between insulin resistance and obesity." (PMID 40428311, 2025). "Increased activity of PPARα results in insulin resistance and defects in insulin signalling and STAT3 activity, reducing cardiac function." (PMID 41007642, 2025). "Insulin resistance is an independent pathogenic factor in PCOS, as insulin modulates hormone production, particularly androgens, and influences ovarian polycystic morphology and P450c17 enzyme activation." (PMID 40534880, 2025). "In the context of metabolic syndrome, RC has been identified as a significant contributor to the development of insulin resistance, with the capacity to accumulate in insulin-sensitive organs such as the pancreas and adipose tissue." (PMID 41357322, 2025). "The insulin/IGF-1 axis is stimulated by insulin resistance and compensatory hyperinsulinemia, which promotes cell division and prevents apoptosis." (PMID 41009614, 2025). "Indexes calculated on the basis of fasting insulin and glucose levels, namely the homeostatic model assessment of insulin resistance (HOMA) index and Matsuda index, are the best and most extensively validated indicators for IR diagnosis." (PMID 40141439, 2025). "The state of chronic, low-grade inflammation and hepatic insulin resistance inherent in MASLD impairs insulin clearance, contributing to systemic hyperinsulinemia." (PMID 41441018, 2025). "It has been shown that FGF21 improves insulin sensitivity, insulin resistance and β-cell function, and exerts a protective effect through alleviating ROS-mediated oxidative stress, inflammation and apoptosis." (PMID 39819596, 2025). "Obesity is characterized by chronic low-grade inflammation driven by excessive adipose tissue, which secretes pro-inflammatory cytokines such as TNF-α and IL-6, thereby impairing insulin signaling and inducing insulin resistance." (PMID 41153828, 2025). "Although traditionally viewed as separate mechanisms, many individuals with T2D present features of both impaired insulin secretion and insulin resistance, and their interplay can influence disease severity and treatment response." (PMID 40741412, 2025). "The liver is essential in preserving glucose homeostasis, and hepatic insulin resistance can result in heightened glucose production and diminished insulin clearance—both crucial elements in the pathogenesis of T2DM." (PMID 40444231, 2025). "L-T4 replacement therapy significantly improves insulin resistance markers in the early post-thyroidectomy phase, with the liquid formulation demonstrating greater efficacy in reducing hepatic insulin resistance." (PMID 40863163, 2025).
Insulin resistance (continued). "Transgenic mice with overexpression of IGFBP3 exhibited mild insulin resistance, accompanied by elevated levels of plasma leptin, glucose, and insulin." (PMID 40271123, 2025). "The TyG index, a composite indicator combining fasting blood glucose and triglycerides, serves as a marker of insulin resistance and is classified as an insulin-related metric." (PMID 40895109, 2025). "Insulin resistance - a pathological condition defined by diminished tissue sensitivity to insulin, resulting in impaired glucose regulation - is central to PCOS pathology, affecting up to 70% of women diagnosed with the syndrome." (PMID 40226143, 2025). "Furthermore, since insulin sensitivity- a highly sensitive marker was unavailable for all participants, we could not detect the association between spice and pepper intakes and the risk of insulin resistance." (PMID 39932911, 2025). "The excessive adipose tissue in obesity leads to chronic inflammation and the release of pro-inflammatory cytokines, thereby impairing insulin signaling and leading to insulin resistance." (PMID 39911326, 2025). "The BMI, glucose and insulin concentrations, insulin resistance, and anxiety scores significantly decreased during and after fasting compared to the baseline measurements (all p < 0.05), lasting for two months." (PMID 40630882, 2025). "Obesity, decreased insulin secretion, insulin resistance, oxidative stress, hormonal imbalance, and chronic inflammatory reaction have been associated in the pathogenesis of GDM." (PMID 40621530, 2025). "Both insulin and homeostatic model assessment for insulin resistance (HOMA-IR) showed significantly elevated levels in patients with IR and T2DM compared to control and T2DM without IR." (PMID 41137275, 2025). "In T2DM with insulin resistance, the body secretes more insulin, which hinders the body’s ability to break down fat, to regulate blood glucose levels." (PMID 40547526, 2025). "In type 2 diabetes (T2DM), insulin resistance diminishes the peripheral tissue response to insulin and impairs central nervous system insulin signaling." (PMID 40040744, 2025). "Improves glucose uptake, reduces blood glucose and insulin levels, alleviates insulin resistance, enhances mitochondrial function, reduces lipid accumulation, ameliorates liver steatosis." (PMID 39963239, 2025). "Serine phosphorylation of IRS-1 inhibits this insulin signal transduction and thus results in insulin resistance." (PMID 40274715, 2025). "Studies have shown that APSs can reduce serum GLU levels, increase insulin sensitivity, and reduce insulin resistance." (PMID 40867713, 2025). "It showed a better predictor value for diabetic complications than metabolic syndrome, total daily insulin dose and other insulin resistance estimations." (PMID 39679900, 2025). "This process is compounded by insulin resistance, which diminishes neuroprotective insulin signaling pathways essential for neuronal survival and tau phosphorylation regulation." (PMID 41142156, 2025). "For example, propionic acid enhances insulin sensitivity and reduces insulin resistance in peripheral tissues by activating free fatty acid receptors and promoting the secretion of glucagon-like peptide-1 (GLP-1)." (PMID 40860483, 2025). "Insulin resistance (IR), characterized by reduced insulin sensitivity, serves as an independent predictor of ischemic stroke and contributes to its onset, progression, and prognosis by promoting thrombosis and atherosclerosis." (PMID 40895101, 2025). "It appears that the ketogenic diet can improve insulin sensitivity in just 6 days by reducing fasting insulin concentrations by up to 53%, the insulin resistance index (HOMA-IR) by 57%, and peptide-c by 36%." (PMID 40289934, 2025). "Berberine also ameliorated pathological alterations in islet morphology, improved insulin secretion, and alleviated insulin resistance." (PMID 41471379, 2025).
Insulin resistance (continued). "T2DM is primarily defined by chronic insulin resistance, in which peripheral tissues such as muscle, liver, and adipose fail to respond adequately to insulin." (PMID 40564201, 2025). "SGLT-2i is a valid alternative for patients developing either impaired insulin secretion or insulin resistance." (PMID 40175622, 2025). "Brain insulin resistance in AD means neurons and glia respond poorly to normal (or even elevated) insulin." (PMID 41155642, 2025). "Insulin sensitivity can be assessed by using surrogate indices such as the Matsuda index and the Homeostasis model assessment of insulin resistance index (HOMA-IR)." (PMID 40075777, 2025). "Insulin resistance (IR), which refers to an impaired ability of cells to respond normally to insulin and utilise it for metabolic processes, is considered a key feature of T2DM, often present even before diabetes is clinically diagnosed." (PMID 41165399, 2025). "Additional significant differences were found in post-OGTT glucose concentrations, insulin levels, and indices of insulin resistance and sensitivity, including HOMA-IR, QUICKI, and G/I ratio." (PMID 40806228, 2025). "Conversely, insulin resistance in people with T1DM is often secondary to non‐physiologic exogenous insulin exposure and changes in the anthropometric features during the course of the lifetime in parallel with aging." (PMID 40083078, 2025). "Under obese conditions, a shift toward pro-inflammatory M1 macrophage polarization occurs, accompanied by increased production of cytokines such as TNF-α and IL-6, both of which disrupt insulin signaling and contribute to insulin resistance." (PMID 40869401, 2025). "IGF-1 was inversely associated with age, glycemic markers (fasting glucose, HbA1c), insulin resistance (HOMA-IR), TNF-α, and atherogenic lipids, while higher levels were linked to better insulin sensitivity." (PMID 41393761, 2025). "Between-group comparisons revealed that barley cereal consumption resulted in significantly greater improvement than corn cereal consumption in both fasting insulin (p = 0.038) and insulin resistance (difference: −0.55, p = 0.000)." (PMID 40944189, 2025). "Enhanced lipolysis in the adipose tissues of insulin resistant patients enhances the influx of FFAs to the liver which in turn worsens hepatic steatosis and insulin resistance." (PMID 41220583, 2025). "In the normal or metabolic syndrome conditions, hyperinsulinemia results from either oversecreting of insulin or hepatic dysfunction in clearing excess overproduced insulin, which is responsible for insulin resistance secondary to changes in body weight." (PMID 40901060, 2025). "Studies of mice with global aromatase deficiency consistently show an increased propensity towards obesity and insulin resistance, and mice with adipocyte-specific aromatase overexpression exhibit improved insulin sensitivity and reduced inflammation." (PMID 41180177, 2025). "Altogether, these results point to an early state of hepatocyte insulin resistance that leads to a compensatory beta cell-mediated insulin secretion in mice receiving sEVPA." (PMID 40387904, 2025). "In conclusion, FGF21 demonstrates an irreplaceable role in insulin resistance, both by increasing insulin signaling to enhance glucose uptake and by increasing lipocalin secretion to elevate insulin sensitivity." (PMID 40881124, 2025). "In Type 2 diabetes (T2DM), insulin resistance in peripheral tissues, abnormalities in insulin signaling pathways, and hyperinsulinemia are key contributors to hyperglycemia." (PMID 40724942, 2025). "This process is accompanied by massive reactive oxygen species release and intensified inflammatory responses, triggering systemic inflammation that disrupts insulin signaling pathway efficacy and culminates in insulin resistance." (PMID 40584102, 2025).